IL6 (interleukin 6)
Diseases named in the same sentence as IL6 in open-access papers (continued):
Sharing a sentence is not in itself a finding about the gene and the disease.
prostate carcinoma (continued). "We also describe evidence of immunomodulatory intervention of MGF-AuNPs in prostate cancers through observations of enhanced levels of anti-tumor cytokines, such as IL-12 and TNF-α, with concomitant reductions in the levels of pro-tumor cytokines, such as IL-10 and IL-6." (PMID 34408231, 2021). "The results from a similar longitudinal study of cytokine expression patterns suggested that serum levels of IL-1, IL-2, IL-6 and IFN-γ in patients with prostate cancer during intensity-modulated radiotherapy may be predictive for acute radiation-induced normal tissue toxicity." (PMID 33149212, 2020). "Furthermore, based on survival analysis, clinical stage and IL-6 level (but not CD44 level) had predictive power regarding biochemical failure in prostate cancer patients." (PMID 31315262, 2019). "Importantly, in recent years antibodies (e.g., siltuximab) targeting the IL-6/JAK/STAT3 pathway have been tested as monotherapy or in combination with cytotoxic drugs in various clinical trials for treatment of cancers, including prostate cancer." (PMID 31143708, 2019). "Based on our results, IL-6 signaling mediated the disruption of the complex interplay between primary tumor, the microenvironment, and the transition to more aggressive disease in prostate cancer with or without effective local therapy." (PMID 31315262, 2019). "Although the exact effects or the mechanisms that IL-6 is involved on prostate cancer cells is not yet known, it has been suggested that IL-6 can modulate the metastatic process as well as the transition from hormone-dependent prostate cancer to castration resistance prostate cancer." (PMID 30134795, 2018). "Interestingly, melatonin, which has been shown by us to inhibit constitutively active NF-κB in prostate cancer cells via the membrane G protein-coupled MT1 receptor, reduces both AR-V7-induced NF-κB activation and IL-6 gene transcription in LNCaP and 22Rv1 cells." (PMID 28561752, 2017). "Antibodies against IL-6 (CNTO 328, siltuximab) or the IL-6 receptor (tocilizumab, REGN-88) have been used in several clinical trials in different tumor entities, including multiple myeloma, ovarian cancer, prostate cancer, and renal cell carcinoma, and have been found to be well tolerated." (PMID 25268165, 2014). "Although studies found that plasma and urine IL6 levels were higher in patients with bladder cancer than in healthy controls, unlike prostate cancer, the function of IL6 in bladder cancer remains unclear." (PMID 23762858, 2013). "In prostate cancer, presence of Raf-1 and MEK1 in conjunction with elevated ERK1 and ERK2, and their phosphorylated forms, suggests that stimulation of cell proliferation could be triggered by IL-6 via the ERK pathway." (PMID 22046506, 2012). "However, most of the developed anti-IL-6 monoclonal antibodies have failed clinical trials against solid tumors, including pancreatic cancer, renal cell carcinoma, melanoma, prostate cancer, and colorectal cancer, and thus, they have never been approved for clinical use." (PMID 37887354, 2023). "Previous study found that prostate cancer patients who responded to docetaxel and zolendronic acid therapy had a 35% decrease in overall serum IL-6 levels, while patients who did not respond had an increasing in serum IL-6 levels, which implied IL-6 regulate chemo-resistance in prostate cancer." (PMID 29296206, 2017). "Given the growing evidence that EMT states exist and may contribute to prostate cancer progression and metastasis, it is therefore not surprising that IL-6 signaling is perhaps involved in the processes of prostate cancer-associated EMT during their metastatic dissemination." (PMID 23977098, 2013). "The distinct functions of the two MAPKs may well be reproduced also in prostate cancer cells, as evidenced by our results with the inhibitors PD98059 and SB202190, thus suggesting that also in LNCaP cells p38 MAPK exerts a wider role than ERK1/2 on IL-6 and CCL5 transcription factors." (PMID 19242540, 2009).
prostate carcinoma (continued). "Regarding cytokine levels, the prostate cancer nonsupplemented group exhibited a significant posttreatment increase in TNF-α levels (p=0.036), while IL-6 levels remained unchanged." (PMID 40692981, 2025). "However, despite the positive data in preclinical models, the clinical activity in advanced prostate cancer patients was modest or not significant, suggesting that anti-IL-6 therapies may not be the most effective approach to block STAT3 signaling in this setting." (PMID 31143708, 2019). "IL-6, IL-8, and TNF-α, but not IL-1β, are upregulated in prostate carcinoma (CaP) patients with CC compared with those without CC." (PMID 30513776, 2018). "Levels of IL6 and CXCL8 in pre-operative serum samples were analyzed using ELISA, and concentrations were compared between prostate cancer patients with and without prostatic C. acnes infection using standard statistical methods." (PMID 30473726, 2018). "We then focused on inflammation mediators IL6 and IL8 because of their known role in prostate cancer and their distinct expression pattern in relapse and non-relapse tumors that correlates with that of Egr3." (PMID 23342084, 2013). "Given that IL-6 is exclusively produced in CAFs and not resting fibroblasts, it has been suggested that CAF-derived IL-6 may stimulate VEGF secretion from prostate cancer cells independently of AR signaling via PI3K/AKT, STAT3 and MAPK signaling." (PMID 36671452, 2022). "Furthermore, in survival analysis, clinical stage and overexpressed IL-6 level, but not CD44 level, predicted biochemical failure in prostate cancer patients." (PMID 31315262, 2019). "Indeed, our results showed that the addition of IL-6 to non-ALDHhigh-derived cells resulted in a generation of ALDHhigh subpopulation in PC3M-1E8 cells and primary prostate cancer cells." (PMID 25261365, 2014).
colorectal cancer (636 papers, 2002 to 2026). A primary or metastatic malignant neoplasm that affects the colon or rectum. "IL6 also plays an important role in the development of inflammation-associated colorectal cancer through hyperactivation of IL6/STAT3 pathway." (PMID 41209739, 2025). "Patients with colorectal cancer often have elevated levels of IL-1β, IL-6, and TNF-α, which are associated with aggressive tumor behavior and a poor prognosis." (PMID 41463421, 2025). "Loss of MSH3 function is an acquired somatic defect seen in 50% of colorectal cancers and triggered by proinflammatory interleukin-6 signaling, causing a reversible nuclear-to-cytoplasmic shift of the protein." (PMID 40989818, 2025). "Blocking the interaction of IL-6 and IL-6R in colitis-associated colorectal cancer (CAC) by anti-IL-6 receptor antibodies reduced the size and number of tumors in mice, and the effect was mediated by the downregulation of HIF-1α." (PMID 40430040, 2025). "Elevated IL-6 levels are associated with advanced tumor stages, increased tumor size, metastasis, and shortened survival of colorectal cancer patients." (PMID 40549756, 2025). "The association between IL-6 protein expression and clinicopathological features was assessed in 118 colorectal cancer (CRC) patients." (PMID 41007818, 2025). "In our Kaplan–Meier survival analysis, a significant association was observed between IL-6 expression and overall survival in patients with colorectal cancer (CRC)." (PMID 41007818, 2025). "In colorectal cancer models driven by the loss of adenomatous polyposis coli gene, the up-regulation of gp130 expression leading to a heightened responsiveness to IL-6 and IL-11 also induces Yap1-dependent transcription." (PMID 37957015, 2024). "Our study showed that mini-laparotomy surgery for colorectal cancer was significantly associated with decreased increment of IL-6 at 2 h after surgery [IL-6 (Δ2 h)]." (PMID 38978990, 2024). "In contrast, other studies indicated that Alistipes are pathogenic in colorectal cancer by activating the IL-6/STAT3 pathway." (PMID 38390939, 2024). "In a previous paper, this type of IL-6 production by PBMCs from preoperative colorectal cancer patients was found to be associated with poor over-all survival." (PMID 39518029, 2024). "Previously, in a different mouse model, the genus Alistipes has been shown to positively correlate with IL-6 production and mast cell proliferation, and associated with the colorectal cancer progression in experimental mice." (PMID 39944558, 2024). "This study is a preliminary investigation into the effects of ART1 on the IL-6-induced proliferation of colorectal cancer cells and its potential underlying mechanisms." (PMID 38504172, 2024). "In colorectal cancer, the minimally invasive laparoscopic technique is associated with significantly lower levels of plasma IL-6 after surgery, reduced local inflammation, and better overall outcomes compared to the open procedure." (PMID 38067195, 2023). "Patients with colorectal cancer are found with elevated serum interleukin-6 (IL-6), which is associated with advanced tumor grades and is related to their poor survival outcomes." (PMID 37047623, 2023). "This particular study was also the only one that included patients with colorectal carcinoma, showing that general epidural anaesthesia was associated with elevated IL-6 levels." (PMID 37762967, 2023). "In colorectal cancer, macrophage-derived IL6 in immune microenvironment was associated with chemoresistance." (PMID 35692583, 2022). "The multiple stepwise regression analysis indicates that lymph node metastasis and TNM staging are independent risk factors that correlate with IL-6 and IL-12p70 levels in colorectal cancer patients (P<0.01)." (PMID 36226059, 2022).
colorectal cancer (continued). "A recent study on colorectal cancer reported the release of IL-6 and GM-CSF from cancer-associated fibroblasts, leading to the differentiation of monocytes into tumour-associated macrophages, resulting in an immunosuppressive tumour niche." (PMID 35022523, 2022). "Fourth, during the development of NAFLD, the low inflammatory state caused by TNF-α and IL-6 leads to the disorder of gut microbiota, which can also initiate colorectal cancer." (PMID 36438843, 2022). "It has been suggested that the main sources of interleukin-6 (IL-6) production during colorectal cancer progression are the tumor-associated macrophages, mesenchymal stem cells, or colon cancer-associated fibroblasts." (PMID 33923292, 2021). "High serum concentrations of IL-6 are associated with tumor progression, metastases, and poor clinical outcomes, especially for colorectal cancer patients." (PMID 34829914, 2021). "IL6 ectopic expression enhanced PP242 drug susceptibility in colorectal cancer cells, which completely abolished the activity of mTOR pathway." (PMID 33582655, 2021). "This pathological process is inhibited in IL-6-deficient mice, confirming the paraneoplastic effect of IL-6 in colorectal carcinoma-induced thrombocytosis." (PMID 34322381, 2021). "In colorectal cancer, IL-6/IL-11-dependent STAT3 activation in cancer-associated fibroblasts promoted tumor development and also correlated with poor prognosis." (PMID 32865617, 2020). "Clinical studies revealed that increased serum IL6 concentrations in patients are associated with advanced tumor stages of various cancers (e.g., lung and colorectal cancers) and short survival in patients." (PMID 32308549, 2020). "New data, however, links IL-6 production to cancer associated fibroblasts (CAFs) in human colorectal cancer." (PMID 32317968, 2020). "Chronic inflammation is regarded as an important risk factor for the development of colorectal cancer, and IL-6/STAT3 activation seems to take a center stage in human cancer development." (PMID 32422984, 2020). "Increased levels of TNFα and IL-6 were detected in tumor tissues and sera of patients with colorectal cancer, and these cytokines were associated with increased tumor burden and tumor staging, metastasis, and lower overall survival." (PMID 32317968, 2020). "Other RAB family proteins such as RAB3C have been reported to regulate the secretion of IL6 to promote colorectal cancer metastasis, the underlying mechanism of which still needs to be elucidated." (PMID 33072555, 2020). "Several of the studies with pancreatic cancer and colorectal cancer tested a large number of patients and found a significant association between high circulating IL-6 levels and short OS." (PMID 30038723, 2018). "Three studies investigated the use of serum IL-6 as a diagnostic biomarker in patients with colorectal cancer." (PMID 30038723, 2018). "Elevated levels of IL-23, IL-17, and IL-6 in early stages of colorectal cancer have been associated with adverse prognosis and more aggressive disease." (PMID 30304852, 2018). "Our study revealed that RAB3C overexpression promotes tumor metastasis and is associated with poor prognosis in colorectal cancer, through modulating the ability of cancer cells to release IL-6 through exocytosis and activate the JAK2-STAT3 signaling pathway." (PMID 28784136, 2017). "This study demonstrated that RAB3C overexpression is associated with tumor metastasis and poor prognosis in colorectal cancer, through modulating exocytosis of IL-6 in cancer cells, thus leading to activation of the IL6-JAK2-STAT3 pathway." (PMID 28784136, 2017). "IL-6 expression was associated with tumor stage, size, metastasis and survival of patients with colorectal cancer." (PMID 26258407, 2015). "An increased expression of IL-6 has been associated with an unfavorable prognosis in patients with various types of cancers including colorectal cancer." (PMID 26258407, 2015).
colorectal cancer (continued). "We previously reported that a high G/L ratio prior to surgery is a risk factor associated with the prognosis of patients with colorectal cancer, and that a correlation exists between the G/L ratio prior to surgery and the IL-6 concentration." (PMID 25436003, 2015). "The extent of biological invasion can be determined by the IL-6 levels; in colorectal cancers, IL-6 is reportedly associated with the progression of cancer and prognosis." (PMID 25436003, 2015). "Very recently, we finalized an analysis of pre-diagnostic plasma IL-6 concentrations and risk of colorectal cancer in the CLUE II cohort using 173 incident colorectal cancer cases and 345 matched controls." (PMID 26321888, 2015). "More recently, McMillan’s group has linked mGPS with IL-6 and tumor necrosis in patients with primary resected colorectal cancer." (PMID 25069793, 2014). "IL6 levels are known to be increased in most epithelial tumors, and high serum IL6 levels are associated with poor clinical outcomes in patients with colorectal cancer or ovarian cancer." (PMID 24885802, 2014). "In the IL6 gene, two SNPs, rs1800795 and rs1800796 have been studied in particular detail with colorectal cancer, and rs1800795 has demonstrated positive associations with colorectal cancer." (PMID 24235998, 2013). "For example, interleukin-6-174CC genotype was a risk factor on bladder cancer while tends to be a protector on colorectal cancer and gastric caner." (PMID 21818296, 2011). "Further, several studies have linked IL-6 production with colorectal cancer and levels of serum IL-6 are increased in colorectal carcinoma patients, which further correlated with tumor size." (PMID 20885960, 2010). "The inflammatory process is thought to be a key underlying component of colorectal cancer (CRC) that is initiated by pro-inflammatory cytokines such as IL-6 in response to an inflammatory insult." (PMID 21129206, 2010). "Interleukin-6 (IL-6) has been used for the diagnosis of colorectal cancer and CRP was directly associated with survival/prognosis, but has been less widely used and not yet used serially." (PMID 19948067, 2009). "In a recent study of colorectal cancer, high serum IL-6 levels were linked to the −174 GG genotype, but only in patients with advanced disease." (PMID 14735187, 2004). "Furthermore, IL-6 is a key immunoregulatory factor associated with poor prognosis in cancers such as breast and colorectal cancer." (PMID 41480347, 2025). "Thus, in this study we have examined the possible influence of functional polymorphisms within the IL-6, IL-6R, and gp130 genes in individuals with sporadic colorectal cancer on the occurrence of different types of microsatellite instability." (PMID 39199686, 2024). "Therefore, high levels of M2 macrophage infiltration and IL-6 expression in tumor tissues are significantly associated with poor prognosis in patients with colorectal cancer." (PMID 38627864, 2024). "However, tumor-infiltrating interleukin-6-positive immune cells at the invasive front were associated with significantly longer survival in early-stage colorectal cancer patients." (PMID 39518029, 2024). "Although IL-6 is recognized as a potent inducer of colorectal cancer progression, the detail mechanisms underlying IL-6-induced colorectal cancer epithelial–mesenchymal transition (EMT), one of the major process of tumor metastasis, remain unclear." (PMID 37047623, 2023). "Nevertheless, others have reported that supplementation of VSL3# with anti-inflammatory drug balsalazide in mice with colorectal cancer induced by azoxymethane/dextran sodium sulfate reduces tumor burden in association with increasing Bax/Bcl-2 ratio and lowers IL6/STAT-3 signaling." (PMID 35625485, 2022).